CD4 (CD4 molecule)
Diseases named in the same sentence as CD4 in open-access papers (continued):
Sharing a sentence is not in itself a finding about the gene and the disease.
infection (continued). "After infection with virus in the periphery, iDCs process viral antigens, then differentiate into mature DCs and migrate from peripheral tissues to lymph nodes where they prime naïve CD4 and CD8 T lymphocytes to maintain protective antiviral cytotoxic T cell memory." (PMID 15301687, 2004). "The frequencies of T CD4+CD25+Foxp3+ and CD4+LAP+ cells were investigated by flow cytometry in draining lymph nodes weekly during the infection." (PMID 40745935, 2026). "Shortly after infection, HIV integrates its RNA genome into the host DNA, forming proviral DNA primarily within CD4+ T cells." (PMID 41424846, 2026). "At 6‐, 7‐, and 8‐weeks post‐infection, animals from the Lb/HSP65 group showed a higher frequency of CD4+LAP+ T cells when compared to their control groups." (PMID 40745935, 2026). "Although overall frequencies of memory T cells were comparable between HV and BR groups, CD4+ TEM and GC B cells were significantly enriched in the NP of BR individuals at least 1 year post infection." (PMID 41527553, 2026). "Functional analysis showed that LAG3-expressing CD4+CD44+ T cells secreted elevated levels of interleukin-4 (IL-4) and IL-10 at 2 and 4 weeks post-infection." (PMID 41680821, 2026). "Here, we use CTL-engaging single-chain diabodies to assess the rate of lysis of uninfected and HIV-1-infected primary CD4+ T cells under identical CTL pressure in the settings of both latent and active infection." (PMID 41929103, 2026). "On day 2 post-infection, splenic T-cell subsets (CD3+, CD4+, CD8+) were quantified by flow cytometry." (PMID 41753603, 2026). "Intracellular staining identified multifunctional CD4 and CD8 T cells after both vaccination and infection." (PMID 42238599, 2026). "These women all had detectable C. trachomatis-specific CD4+ T cells in blood; however, the magnitude of the response was 2.4-fold lower than in NAAT-/Ab + (cleared infection) or NAAT+/Ab- (primary infection) groups." (PMID 41334931, 2026). "multilocularis infection, LAG3-/-CD4+ T cells exhibited a greater propensity to differentiate into CD4+ effector T (Teff) cells and produced higher levels of IFN-γ and IL-10 in both the livers and spleens of recipient mice." (PMID 41680821, 2026). "Together, these findings identify CD73 ectoenzyme as a critical immunometabolic checkpoint that modulates CD4 CTL responses, revealing a dual role for this pathway in controlling infection and limiting tissue damage." (PMID 42206042, 2026). "This enhancing activity was observed for direct infection of TZM-bl reporter cells and primary CD4+ T cells, as well as trans-infection in the presence or absence of the mannose-binding host lectin DC-SIGN." (PMID 42146538, 2026). "Natural regulatory T cell levels (CD4+, CD25+, and Foxp3+) are significantly increased in Giardia infection." (PMID 41970608, 2026). "Expansion of HIV specific T cells reaches a peak three weeks after infection and can be traced by cell-surface expression of CD38 and the human leukocyte antigen-D related (HLA-DR) markers on CD4 and CD8 T cells." (PMID 41373539, 2025). "GFP-positive cells were enumerated within the CD4/CCR5 positive gate and virus titers (transducing units per milliliter; TDU/mL) were determined for those samples falling within the linear infection range (n = 2 titration points)." (PMID 40366257, 2025). "An enrichment of naïve CD4 and CD8 T-cells was still evident in the transgenic mice, despite the expected differentiation of T-cells from a naïve to a memory phenotype during infection." (PMID 40720380, 2025). "The proportion of IL-2 and IFN-γ secreted by CD4+CD44+ and CD8+CD44+ T cells in the vaccine immunization group exhibited a significant increase compared to the PBS + infection and CpG + infection group." (PMID 40266142, 2025).
infection (continued). "In contrast, minimal NET accumulation was detected in lesions of C57BL/6 mice at day 20 after infection, despite the marked effects of IFNAR blockade on lesion Ly6G coverage and CD4+ T cell accumulation at this time point in C57BL/6 mice." (PMID 40986319, 2025). "Low naïve CD4+ counts among older Tsimane adults with CO suggests that these individuals may have a depleted capacity to mount immune responses to previously unencountered infections and points to influence of childhood physiological stress on trajectories of disease experience." (PMID 40668911, 2025). "Three days post-infection, group 1 ILCs, CD8+ T cells, CD4+ T cells, and monocytes were the main IFN-γ producers." (PMID 40169810, 2025). "L'infection VIH avait été diagnostiquée 12 ans auparavant, traitée par abacavir/dolutegravir/lamivudine (charge virale indétectable, CD4 : 779/μl)." (PMID 40248582, 2025). "Among six HAM patients, 81.4 ± 4.3% (mean ± SD) of infected cells were CD4+, compared to 12.5 ± 8.5% that were CD8+, demonstrating a significantly higher frequency of infection in CD4+ T cells." (PMID 40004169, 2025). "Further analysis using flow cytometry found that the cell numbers of CD11c+CD4+TEM per milliliter increased at 12 h and returned to baseline levels at 48 h post-infection." (PMID 40237529, 2025). "While CD4+ and CD8+ conventional T (Tconv) cells produced lower amounts, Areg was also induced with infection." (PMID 41094201, 2025). "PPRV nucleoprotein expression was predominantly found in the CD4 T cells starting at 5 dpi, specifically during MA08 infection." (PMID 39992151, 2025). "We conclude that microglia, CD4 + T cells, and macrophages primarily contribute to the overall production of IFN-γ following an intranasal infection with JHMV." (PMID 40471948, 2025). "Clusters 1–3 possessed a CD4 signature and represented a major fraction of CD3+ cells at days 7 and 14 after infection, validating our flow cytometry findings." (PMID 39989461, 2025). "In areas where HIV and filarial infections co-occur, previous studies have found an expansion of activated CD4 T cells (as measured by HLA-DR and HLA-DR/CD38 expression) in WB infections." (PMID 41295582, 2025). "Early in the infection, there is typically an increase in the proportion of highly activated (CD38+) and proliferating (Ki-67+) CCR5+CD4+ T cells." (PMID 40141240, 2025). "In the blood, the proportion of CD3+, CD3+CD4+, and CD3+CD8+ T cells were significantly deceased in the infection group compared with the control group (p < 0.001)." (PMID 40305201, 2025). "We additionally visualized the relationship between frequency of these CD4 and CD8 T cell subsets and infection both pre- and post-transplant." (PMID 40475763, 2025). "CD4+CTLs are critical to take care of viral [such as Epstein-Barr virus (EBV), Herpes Simplex virus (HSV), and cytomegalovirus (CMV)] infections, which evade their MHC-I recognition to escape classic CD8+CTLs." (PMID 41009359, 2025). "Long-term infections (>6 months post-seroconversion; median ART duration: 35 months; median CD4 counts: 326.5 cells/μL) were noted in 83.3% of PLHIV." (PMID 41012660, 2025). "The populations of CD4+ and CD8+ T cells were also much lower in the mice infected with wild-type K7, but the numbers of these anti-infection adaptive immune cells were also significantly increased by IFA, which was consistent with the increase in IFN-γ." (PMID 39761301, 2025). "To compare the antiviral response in LPR and GLD mice during primary infection and latency, we counted the numbers of CD4+ T cells and CD8+ T cells in the brains and TGs at 7 and 120 days of infection using flow cytometry." (PMID 41439958, 2025). "While both CD4+ and CD8+ T cells contribute to infection control, CD8+ T cells and their production of IFN-γ play a dominant role." (PMID 40936724, 2025).
infection (continued). "At 6 months after infection, the number of cells expressing PD-1+, CTLA-4+ in CD4+ and CD8+ cells were higher than that at 3 months after infection; A previous study demonstrates that PD-1 expressing SARS-CoV-2 specific CD4+ T cells were exhausted." (PMID 40416973, 2025). "For this, CD4 + T cells were infected at an MOI of 5, and luciferase activity was measured 24 hours post-infection across the indicated experimental conditions." (PMID 40632811, 2025). "As anticipated, all CD4 and CD8 T cells present at the site of infection exhibited the CD62L- phenotype, indicative of activation." (PMID 40720541, 2025). "In conclusion, our data demonstrate that SIVmac239 infection of female RMs results in clinical signs of acute SIV infection, including high VL and depleted CCR5+ CD4+ T cells, which resolve following 2 months of ART." (PMID 40504034, 2025). "Although antigen presentation is not strictly required for transinfection, T-cell activation greatly increases in productive infection and unsurprisingly, HIV-specific activated CD4+ T cells are the main target of HIV-1 infection." (PMID 41373539, 2025). "Treg control the magnitude of pro-inflammatory CD4 and CD8 T cell responses during infection, counteracting conventional T cell activation." (PMID 41159501, 2025). "Specifically, ECs demonstrated significantly low-level BTLA expression in CD4+ T cells (21, 49, 84, and 133 days post-infection), as well as diminished TIGIT expression in CD8+ T cells (49, 84, and 133 days post-infection) compared to PGs." (PMID 40637373, 2025). "In cardiac tissue, before infection, the frequencies of CD39+ and CD73+ CD4+ T cells were similar, with relatively low coexpression levels (36.3% ± 11.6% for CD39+, 29.6% ± 8.2% for CD73+, and 10.8% ± 1.6% for CD39+CD73+)." (PMID 40590226, 2025). "All four subsets (Th, CTL, CD4+CD8+, CD4−CD8−) were affected by infection, with a decrease in their levels as early as 2 dpi." (PMID 41150385, 2025). "Following the infection, WC1+ γδ, NK, CD4-CD8+, CD4+CD8-, CD4+CD8+ T cells and NK cells all exhibited a significant increased percentage of the CD44 High phenotype." (PMID 41573562, 2025). "Evaluation of markers found to be in common between association with both transplant impact and infection confirmed the key role of CD4 CM, CM 25+ and EM TIGIT T cells in both impact of transplantation and prediction of infection." (PMID 40475763, 2025). "Whereas most transmitted HIVs are R5 tropic, naive CD4+ T cells express CCR5 only transiently and are relatively resistant to infection with R5-tropic virus in vitro." (PMID 40048262, 2025). "HCV antigen–stimulated CD4+ T cells produced IL-21, IFN-γ, and TNF at the week 8 or 11 peak and at lower frequencies at week 20 or 24 after infection." (PMID 40956619, 2025). "In the analytic dataset with infection stage defined (n = 197; 54 EARLY, 143 long-term), VL was missing in 1 case (0.51%) and CD4 was missing in 1 case (0.51%)." (PMID 41229481, 2025). "Initial studies evaluated high content analysis of infectious titer using an R5 tropic viral stock, HIV-1ADA, generated via infection of CEM•SS cells, titering viral stocks in parental (CD4+/CCR5−) and Hi-5 (CD4+/CCR5+) GHOST cells in 6 well plates." (PMID 40631301, 2025). "As maturation drives the migration of DCs to CD4 T cells (HIV’s primary target), this presents an ideal opportunity for the virus to gain transport from the site of infection to its target cell." (PMID 40929143, 2025). "Some reports have found a higher frequency of triple-producing CD4+ T cells (IFN-γ, IL - 2, and TNF-α) in patients with active TB disease in comparison to patients with latent TB-infection." (PMID 40990013, 2025). "Further, scRNA-seq data revealed that infection with SARS-CoV-2 rewired the gene expression profile of NK, monocytes, CD4+, CD8+ effector T cells and antibody producing B cells in convalescent pregnant women." (PMID 40661959, 2025).
infection (continued). "In this example, CD4+ and CD8+ T cell aggregation increased on days 1 and 2 post-infection, respectively, with the concomitant increase in scanning behaviour and decrease in meandering and directed motion." (PMID 39994207, 2025). "Similar trends were observed for CD4+ and CD8+ T cells, with the group treated with SSO up to 2 h before infection showing the lowest levels of all these immune cells." (PMID 40137298, 2025). "However, CD4-deficient mice were not susceptible to infection with C. difficile, but defective IFN-γ is associated with worsened disease, indicating that IFN-γ produced in early stages of infection by ILCs, and possibly NK cells, plays a major role in host protection." (PMID 40590563, 2025). "Early in infection, at TP1, DENV2 NS3-specific CD4+ T-cells mainly produce IFN-γ and CD107a, with a stepwise increase of IFN-γ production observed from non-SD to SD HW and SD OW/OB patients." (PMID 40595657, 2025). "CD4 T cells (31.4%) were the predominant subset prior to HTNV infection, whereas CD8 T cells (44%) became the dominant population post-infection." (PMID 41460167, 2025). "This persistent infection is largely maintained within central memory (TCM), transitional memory (TTM), and effector memory (TEM) CD4+ T cells, whose long-term survival depends on cytokines engaging the common γ-chain receptor." (PMID 41009690, 2025). "CD4, the primary receptor for HIV-1 entry, is downregulated post-infection to prevent superinfection, enhance viral replication, and evade immune surveillance." (PMID 40699766, 2025). "We found that at 5 days post infection (dpi), there was a clear effector CD4+ T cell (CD44+) population emerging while the majority of CD4+ T cells were still of naive phenotype (CD44–) (left)." (PMID 40777021, 2025). "To further understand how dexamethasone influences an early antiviral response in HSV-1 infection, we measured the counts of NK cells, CD4+ T cells, CD8+ T cells, and HSV-1-specific CD8+/SSIEFARL+ T cells in the brains at 7 days of infection by flow cytometry." (PMID 41439958, 2025). "In fact, we have demonstrated that M-Sec promotes cell-to-cell infection of human immunodeficiency virus type 1 (HIV-1) in macrophages, and HTLV-1 in CD4+ T cells." (PMID 39869648, 2025). "During WNV neuroinvasion, monocytes, neutrophils, NK cells, DC cells, and effector CD4+ and CD8+ T cells were found to infiltrate the brain to respond to the infection." (PMID 40632810, 2025). "This was accompanied by markedly increased total and CD44+ CD62L− CD4+ T cell numbers in lungs of C57BL/6 than C3HeB/FeJ mice by 28 days after infection with 6C4 or 4I2." (PMID 40986319, 2025). "In monocyte-derived macrophages (MDMs) and HeLa-CD4 cells infected with Vpr-expressing HIV-1, nuclear levels of REAF are markedly reduced within two hours post-infection." (PMID 40699766, 2025). "Studies in mice that have demonstrated a requirement for CD4 and/or CD8 T cells in heterosubtypic infection have mainly examined viral titers at day 5–7 following re-infection." (PMID 40750594, 2025). "Upon infection of the skin or mucosal epithelium, HSV undergoes local replication and is controlled by virus-specific CD8+ and CD4+ T cell responses." (PMID 39994207, 2025). "The Pro10, Pro20, Pro40, Amo20, and Pro20 + Amo20 groups showed increased proportions of CD3+, CD3+CD4+, and CD3+CD8+ T cells compared with the infection group (p < 0.01)." (PMID 40305201, 2025). "CD4+ and CD8+ T cells, as well as macrophages, demonstrated a shift from OXPHOS dependence to glycolysis dependence during infection, consistent with activation." (PMID 41472679, 2025). "We transferred Smarta WT or IFN-γ−/− CD4+ T cells into WT or IFN-γ−/− recipients and assessed Smarta polarization post-infection." (PMID 40169810, 2025).
infection (continued). "While this would argue against a neuroprotective effect of Treg-derived Areg in the CNS, we saw an unexpected decrease in IFN-γ production by CD4+ T cells and corresponding increase in brain CFU in Aregflox/floxFoxp3Cre-ERT2 mice at a late infection stage." (PMID 40766255, 2025). "We collected blood from 91 patients before and then 3 months after kidney transplantation and analyzed CD4 and CD8 T cell phenotypes to determine the impact of immunosuppression on immune maturation, senescence, and infection." (PMID 40475763, 2025). "In the chimeric IFNAR–/– model, mice depleted of CD8+ or CD8+ and CD4+ cells largely survived lethal LASV challenge, whereas those depleted for CD4+ cells succumbed to infection." (PMID 40996813, 2025). "Type I interferons (IFNs) are key drivers of antigen-specific Th1 CD4+ T-cells and cytotoxic CD8+ T-cells during infection (3, –, 6)." (PMID 39692514, 2025). "While vaccination alone was shown to elicit robust SARS-CoV-2 Spike-specific CD4 T-helper responses and low-level CD8 T-cell immunity, infection induces enhanced CD8 T-cell immunity." (PMID 40552302, 2025). "Depletion of either CD4 or CD8 in C57Bl/6 mice is insufficient for productive infection, whereas CD3 depletion renders mice competent for infection." (PMID 40430784, 2025). "Studies have shown that CD4+ and CD8+ memory T cells are significantly affected, reducing their population post-infection." (PMID 40181820, 2025). "A model incorporating increased frequency CD4 EM TIGIT+ T cells and ATG induction was predictive of development of infection after kidney transplantation (HR 3.73, CI 1.08-12.9)." (PMID 40475763, 2025). "All ECs in the study were not on antiretroviral therapy and, even during this long period of infection, maintained more than 70% of HIV-1 viral load measurements undetectable and stable CD4+ T lymphocyte counts > 500 cells/mm3." (PMID 40608594, 2025). "To characterise the functional profiles of SARS‐CoV‐2‐specific memory CD4 T‐cell subsets during early convalescence, we performed unsupervised clustering analysis on AIM+ CD4 T cells obtained 1–3 months post infection (T1)." (PMID 41427434, 2025). "Recent publications assessing CNS CD4+ T cells and myeloid cells during acute SIV infection provide valuable insight into the dynamics and infection of these immune cells." (PMID 40099824, 2025). "HIV-1 uses CD4 as viral receptor and CCR5 or CXCR4 as viral coreceptors, with CD4+ helper T cells being the main target of infection." (PMID 39842407, 2025). "H9N2-infected mice exhibited significantly reduced CD4+/CD8+ ratios at both 3 and 6 days post-infection compared to uninfected control mice (P < 0.01), indicating severe immune dysregulation induced by the virus." (PMID 40406095, 2025). "Following infection and viral replication, the frequency of activated (CD38+HLA-DR+) CD4+ and CD8+ T cells increased rapidly, consistent with HIV-1-induced inflammation and the emergence of HIV-1-specific T cell responses." (PMID 41279654, 2025). "However, the high CD4 cell count (450/μL) may indicate that the primary infection was recent." (PMID 39964593, 2025). "In the spleen, the proportions of CD3+, CD3+CD4+, and CD3+CD8+ T cells were increased in the infection group compared with the control group (p < 0.001)." (PMID 40305201, 2025). "Taken together, these findings suggest that Themis promotes virus-specific CD4+ T cell expansion and differentiation into the TFH cell lineage early in infection." (PMID 40777021, 2025). "Following influenza virus infection, IL-18Rα on CD4 and CD8 T cells was steadily upregulated from the onset of infection, peaking at 6 dpi before gradually returning to baseline levels by 28 dpi." (PMID 41285788, 2025). "CD4-depleted macaques also showed increased ADE potential, particularly against ZIKV, and elevated anti-NS1 IgG titers that persisted one-year post-infection." (PMID 41295476, 2025).